YAP1 (Yes1 associated transcriptional regulator)
Diseases named in the same sentence as YAP1 in open-access papers (continued):
Sharing a sentence is not in itself a finding about the gene and the disease.
pancreatitis (10 papers, 2012 to 2025). Inflammation of the pancreas. "First, deleting Mst1&2 with an inducible acinar cell-specific Cre or overexpressing YAP1 in the pancreas reproduced the Mst1&2 whole pancreas epithelial knockout phenotype – acinar atrophy, ductal expansion, and pancreatitis-like phenotype." (PMID 39051998, 2024). "The present study therefore establishes for the first time the induction of four molecules, AGR2, EGFR, YAP1, and AREG, each of which have been individually associated with tissue regeneration in other organs, but are now all activated during pancreatitis." (PMID 27764193, 2016). "Nonetheless, the overall expression of YAP1 in the tumor is significantly higher than in the normal pancreas and pancreatitis cases (p-value = 0.011)." (PMID 22396793, 2012). "In some normal pancreas and pancreatitis tissues we observed moderate to strong YAP1 staining in the acinar cells and small ducts." (PMID 22396793, 2012). "Both we and others have found SMAD4 and YAP1 nuclei staining in ADM of human pancreatitis tissue." (PMID 38247878, 2024). "However, YAP1 is expressed in ADM structures in human pancreatitis tissue, supporting the idea that the two pathways converge during ADM." (PMID 38247878, 2024). "HE staining revealed that ablation of YAP1/TAZ rescued the pancreatitis phenotype of PL mice." (PMID 31513574, 2019). "Thus, consistent with previous work, pancreatitis-associated AGR2 expression initiates EGFR cell signaling, activates YAP1, and induces AREG expression." (PMID 27764193, 2016). "In addition, the Hippo signaling coactivator YAP1 was evaluated in the context of AGR2 expression during pancreatitis." (PMID 27764193, 2016). "YAP1 activation was also dependent on pancreatitis-induced AGR2 expression." (PMID 27764193, 2016). "YAP1 activation has been reported to cause pancreatitis in mice, which was not seen in IGS mice." (PMID 39720531, 2024). "Whether AGR2 expression also results in YAP1 activation in pancreatitis was explored." (PMID 27764193, 2016). "We next focused on examining the expressional patterns of PAF1, YAP1, and TEAD1 in cerulein-induced wild-type (WT) and KrasG12D, Pdx-1 Cre (KC) pancreatitis mouse models." (PMID 36180487, 2022). "The fact that the nuclear expression of YAP1 and TAZ has been found in human pancreatic cancer and pancreatitis samples strongly suggests that the Hippo pathway may play important roles in the pathogenesis of pancreatic disease." (PMID 31513574, 2019). "EGFR inhibition with AG1478 in wild-type mice with pancreatitis still exhibited a significant increase in nuclear YAP1, which was absent in the AGR2-/-null mice." (PMID 27764193, 2016). "Consistent with our findings on the activated Hippo pathway in ductal and AD cells, we stained normal and pancreatitis tissue arrays and found that YAP1 was expressed in ductal cells but not acinar cells in normal human pancreas, as well as in ADM structures in human pancreatitis tissue." (PMID 38247878, 2024).
Poroma (10 papers, 2019 to 2026). A benign adnexal neoplasm composed of EPITHELIAL CELLS. "Overall, YAP1 fusions were expressed in 92% of poromas and 7% of porocarcinomas, with 1 poroma associated with a WWTR1 fusion." (PMID 37627947, 2023). "Recently, studies identified fusions in the YAP-1 gene associated with poroma and porocarcinoma oncogenesis, which could be targeted by future immunotherapies." (PMID 35456278, 2022). "Recent sequencing of these tumors demonstrated that 90% of poromas and ~70% of porocarcinomas exhibit YAP1 or WWTR1 gene fusions, with YAP1 fused to either MAML2 or NUTM1 and WWTR1 fused to NUTM1." (PMID 40491864, 2024). "This suggests that YAP1 fusions are highly recurrent and specific to poromas and porocarcinomas among skin neoplasms." (PMID 37627947, 2023). "Most poromas and porocarcinomas harbor YAP1::MAML2/NUTM1 or, rarely, WWTR1::NUTM1 fusions." (PMID 41350449, 2025). "In this study, YAP1 fusions were present in 88.5% of poromas and 63.6% of PC." (PMID 38891945, 2024). "A loss of YAP1 expression, without a fusion product, is not specific for poroma or PC as it could be detected in nearly all MCCs and in a minority of SCCs." (PMID 38891945, 2024). "In Case 3, the fusion assay identified a YAP1-MAML2 fusion involving exon 4 of YAP1 and exon 2 of MAML2, similar to those reported in poromas." (PMID 31906059, 2019). "YAP1 or TAZ rearrangements have been detected in epithelioid hemangioendothelioma, pseudomyogenic hemangioendothelioma, ependymoma, epithelioid hemangioma, and, lately, in poroma and porocarcinoma." (PMID 37627947, 2023). "Immunohistochemically, EMA and CEA confirmed ductal differentiation, while preserved YAP1 and negative NUT staining supported a lineage distinct from conventional poroma." (PMID 41995819, 2026).
cardiac hypertrophy (9 papers, 2020 to 2025). "To further validate the role of the YAP1/AKT/GSK3β signaling in cardiac hypertrophy, we employed H9c2 cells to elucidate the underlying mechanisms." (PMID 39937832, 2025). "Derived from the YAP1 gene, circYAP1 is crucial in reducing cardiac fibrosis and influencing cardiac hypertrophy through its unique protein interactions." (PMID 41154685, 2025). "The data indicate that lncExACT1 and DCHS2 are new regulators of cardiac Yap1, playing a role in exercise-induced cardiac hypertrophy and cardiomyogenesis." (PMID 40463932, 2025). "Together, circYAP1 and YAP1 mitigate cardiac hypertrophy and fibrosis, highlighting their potential as therapeutic targets in the management of hypertrophic and fibrotic heart diseases." (PMID 41154685, 2025). "Research indicates that activating YAP1 supports cardiomyocyte growth and survival, potentially mitigating myocardial hypertrophy and HF." (PMID 39937832, 2025). "DEGs between the control group and the ISO-treated group of rats were subjected to GSEA, revealing that the Hippo signaling pathway was highly expressed in the hearts of ISO-induced myocardial hypertrophy rats, including YAP1." (PMID 40919415, 2025). "To further assess the impact of YAP1 activation on cardiac hypertrophy, we created mice carrying Myh6CreERT2 and H11CAG-LSL-YAP1 alleles." (PMID 36276651, 2022). "Heterozygous cardiac-specific YAP1-KO mice exhibit increased cell apoptosis and fibrosis; however, adaptive cardiac hypertrophy is attenuated after MI and acute PO." (PMID 35327528, 2022). "Overexpression of Dnm1l and Mfn1 synergistically rescued YAP1-induced mitochondrial damages and cardiac hypertrophy." (PMID 36276651, 2022). "Therefore, our findings suggest that LIMD1 improves outcomes in post-HF pathological cardiac hypertrophy by targeting the YAP1/AKT/GSK3β signaling pathway." (PMID 39937832, 2025). "The YAP1/AKT/GSK3β signaling pathway plays a significant role in cardiac hypertrophy." (PMID 39937832, 2025). "We then examined the impact of YAP1 depletion on AAC-induced cardiac hypertrophy." (PMID 36276651, 2022). "Therefore, the inhibition of Yap1 helps maintain the normal morphology of cardiomyocytes, meaning that verteporfin represents a promising candidate for treating cardiac hypertrophy." (PMID 36276651, 2022). "Certain levels of YAP1 are necessary to induce adaptive cardiac hypertrophy after PO." (PMID 35327528, 2022). "Therefore, targeting YAP1 activation could be a vital approach for reversing pathological myocardial hypertrophy." (PMID 39937832, 2025). "Consequently, the effects noted on cardiac hypertrophy may be facilitated by Yap1-independent mechanisms downstream of lncExACT1 and DCHS2." (PMID 40463932, 2025). "Finally, Verteprofin was used to inhibit YAP1 to rescue cardiac hypertrophy." (PMID 36276651, 2022). "Mechanistically, both in vivo and in vitro experiments demonstrated that overexpression of LIMD1 significantly inhibits the activation of the YAP1/AKT/GSK3β signaling pathway, thereby reversing pathological cardiac hypertrophy induced by pressure overload." (PMID 39937832, 2025). "Heterozygous cardiac-specific YAP1 KO mice, when subjected to TAC, present blunted cardiac hypertrophy and amplified CM apoptosis and fibrosis, with resultant cardiac dilatation and dysfunction." (PMID 32390875, 2020). "Consistent with this, YAP1 deletion in the postnatal heart using Tnnt2-Cre does not significantly affect physical cardiac hypertrophy." (PMID 32390875, 2020).
Ewing sarcoma (9 papers, 2017 to 2025). A small round cell tumor that lacks morphologic, immunohistochemical, and electron microscopic evidence of neuroectodermal differentiation. "In parallel, ROR1/2 upregulate BMI1, a stem cell factor demonstrated to stabilize nuclear YAP1 in Ewing sarcoma." (PMID 32326412, 2020). "In addition, studies by Huimou Chen and others have reported that AURKA induces apoptosis and ferroptosis in Ewing’s sarcoma cells through the NPM1/YAP1 axis." (PMID 38673957, 2024). "Researchers found that Aurora kinase A (AURKA) induced apoptosis and ferroptosis in Ewing’s sarcoma cells by inhibiting the NPM1/YAP1 axis, suggesting that AURKA may be a potential target for Ewing’s sarcoma." (PMID 39314848, 2024). "Mimicking Ewing sarcoma in mice has been challenging, however, a recent mouse model showed that while EWSR1::FLI1 may be sufficient for tumorigenesis, subsequent YAP1 activation induced by IGF1 signalling may be required for the activation of TEAD driven transcription and metastatic progression." (PMID 40442778, 2025).
metastatic tumors (9 papers, 2007 to 2025). "Altogether, these data support the key role of YAP1 in metastasis, which is translated in our data showing an association between increased YAP1 expression and recurrent and/or metastatic disease in pediatric ACT." (PMID 27705928, 2016). "In pediatric ACT, YAP1 mRNA overexpression was associated with death, recurrent/metastatic disease and lower overall survival." (PMID 27705928, 2016). "To further examine the mechanism underlying the association between YAP1 and metastasis, we screened the human GEO database to identify differences in NMU and YAP1 mRNA expression between primary and metastatic tumors." (PMID 31575084, 2019). "Our results open the possibility of future molecular therapies targeting Hippo/YAP1 signaling and linked pathways to treat ACT patients with invasive, recurrent and/or metastatic disease." (PMID 27705928, 2016). "Interestingly, several genes in this cluster or their homologs involved in angiogenesis and inhibition of apoptosis have previously been associated with metastatic tumor progression in murine SCC or human HNSCC (IL6, IL8, YAP1, and BIRC2), and shown to be regulated by NF-κB." (PMID 17498291, 2007). "Using a commercially available (#CO953; BioMax) CRC tissue microarray, we found that 80% of metastatic tumors (n = 10) showed nuclear expression of MUC13 and YAP1." (PMID 37793774, 2023). "Collectively, our analysis of single cell sequencing data suggested that the TME of primary tumor of NSCLC are enormously immunosuppressive than the metastatic tumor and are populated by high expression levels of EGFR/MAP2K1/MTOR/TEAD1/YAP1 within tumor microenvironment of NSCLC." (PMID 35655775, 2022). "Interestingly, the transcription factor YAP1 consistently showed low expression levels irrespective of the sample type, whereas TIGIT, an immune checkpoint that plays a pivotal role in immune suppression, was overexpressed in the vast majority of both primary and LN metastatic tumors." (PMID 40107154, 2025).
Obesity (9 papers, 2020 to 2025). Accumulation of substantial excess body fat. "Most importantly, SENP3 deficiency reduces YAP1 protein level in adipose tissue during obesity." (PMID 38070059, 2023). "Our study indicates that Nar can promote autophagy and reduce excessive fat accumulation by regulating hlh-30, lgg-1, unc-51, pha-4, skn-1, yap-1, and other genes associated with lipid levels, providing a theoretical basis for the prevention of diabetes and obesity." (PMID 36839265, 2023). "In summary, we provided the first evidence that SENP3 accumulates in ATMs of adipose tissue during diet and age-induced obesity, which promotes macrophage infiltration in adipose tissue and systemic inflammation via regulation of YAP1 SUMOylation." (PMID 38070059, 2023). "To further define the in vivo role of SENP3 in YAP1 signaling and obesity, we investigated the in vivo expression of SENP3 and YAP1 in adipose tissue of Senp3flox/flox; Lyz2-Cre mice and Senp3flox/flox littermates." (PMID 38070059, 2023). "Meanwhile, obesity increased messenger RNA (mRNA) level of Hippo pathway effectors Yap1, Wwtr1 (Taz), and their downstream targets, such as Ctgf and Cyr61." (PMID 36229481, 2022). "In conclusion, our current study highlights the role of miR-320-3p on CFL2 expression, YAP1 activation, and myoblast differentiation and suggests that PA-inducible miR-320-3p is a significant mediator of muscle wasting in obesity." (PMID 35054986, 2022). "In addition, myeloid-specific SENP3 deletion attenuated HFD and age-induced obesity and systemic inflammation, which was partially mediated by YAP1 SUMOylation change." (PMID 38070059, 2023). "In addition, fatty acid accumulation increases obesity-associated proteins in NASH-HCC, such as junctional protein associated with coronary artery disease (JCAD), and promotes activation of Yes-associated protein 1 (YAP1), which is essential for tumor growth." (PMID 36612019, 2022). "In this present study, we assessed the expression and function of macrophage SENP3 in adipose tissue during obesity; we also examined the SUMO modification of YAP1." (PMID 38070059, 2023). "In the context of HFD-induced obesity in mice, SENP3 regulates the deSUMOylation of YAP1, while the absence of SENP3 can abolish the upregulation of YAP1 induced by IL-1β." (PMID 39431155, 2024).
renal fibrosis (9 papers, 2016 to 2026). A final common manifestation of a wide variety of chronic kidney diseases characterized by glomerulosclerosis and tubulointerstitial fibrosis. "Consistent with in vitro findings, in the UUO mouse model, endothelial-specific deletion of YAP1 or administration of PD173074 significantly attenuated renal fibrosis, inflammatory responses, and vascular dysfunction, while preserving renal function." (PMID 42051262, 2026). "This study aims to investigate the role of fibroblast growth factor receptor 1 (FGFR1) as an upstream regulator of YAP1 in renal fibrosis and to evaluate the therapeutic potential of targeting this signaling axis." (PMID 42051262, 2026). "Collectively, these results suggest that PKM2 regulates TEAD2 expression and may contribute to renal fibrosis progression by modulating CCN2 expression in tubular epithelial cells through the formation of transcriptional complexes with YAP1 and β-catenin." (PMID 41380965, 2025). "Similarly, elevated YAP1 levels in tubule cells have been previously reported, and inhibiting the YAP1 activity through pharmacological or genetic means has shown promising results in ameliorating renal fibrosis, inflammation, and oxidative stress in experimental type 1 diabetes-related DKD models." (PMID 39608245, 2024). "Furthermore, mice with nephric duct-specific deletion of Yap1 exhibited defects in ureter-bladder junction, and renal tubule-specific Mst1/2 deletion induced hyperproliferation of renal tubular epithelial cells and renal fibrosis." (PMID 34545930, 2021). "The YAP1–TEAD axis promotes cell proliferation, epithelial-mesenchymal transition (EMT), and extracellular matrix production, thereby contributing to renal fibrosis." (PMID 41380965, 2025). "YAP1 inhibition by Verteporfin impairs TGF-β-induced Smad2/3 nuclear accumulation and transcriptional activity to attenuate renal fibrosis in response to mechanoregulators of organ stiffening." (PMID 35356283, 2022). "Given that TGF-β1 treatment increased TAZ protein levels, but not YAP1 protein levels, and that Sav1 depletion activated YAP1/TAZ target gene transcription, we examined TAZ mRNA expression in kidney tissues and assessed the functional role of TAZ in renal fibrosis." (PMID 27550469, 2016). "Our observations indicate that CTGF mRNA expression was enhanced by YAP1/TAZ activation, which may exacerbate renal fibrosis." (PMID 27550469, 2016). "In this study, we demonstrated that PKM2 serves as a cofactor in the regulation of CCN2 expression and may contribute to the progression of renal fibrosis by regulating YAP-TEAD and CCN2 expression in proximal tubular epithelial cells by forming transcriptional complexes of YAP1 and β-catenin." (PMID 41380965, 2025). "In addition, miR-101a could target and downregulate KDM3A expression, which led to elevated TGIF1, inhibited expression of Collagen I (Col1a1), fibronectin, α-SMA, YAP1, and TGF-β2 along with the extent of Smad2/3 phosphorylation, as well as delayed renal fibrosis degree." (PMID 32092824, 2020).
soft tissue sarcoma (9 papers, 2012 to 2025). A malignant neoplasm arising from muscle tissue, adipose tissue, blood vessels, fibrous tissue, or other supportive tissues excluding the bones. "In soft-tissue sarcomas, researchers have discovered that the transcriptional co-activator YAP1 plays a significant role in tumor cells." (PMID 40242775, 2025). "In this study, we report such a case of a soft tissue sarcoma displaying an unusual morphology and immunoprofile, which remained unclassified even after a YAP1::KMT2A fusion was detected." (PMID 40879254, 2025). "In soft tissue sarcomas, YAP1 is a significant transcriptional co-activator." (PMID 40242775, 2025). "These two entities may therefore define a biologically distinct subgroup of soft‐tissue sarcomas in which aberrant YAP1/Hippo signaling is activated by chimeric transcription factors." (PMID 30898787, 2019). "Comprehensive molecular characterization pipelines are needed to screen patients with advanced soft‐tissue sarcomas for the presence of druggable alterations, including but not limited to nuclear YAP1 expression in MLS, to facilitate treatment decisions and advance therapy." (PMID 30979710, 2019). "This cohort included 15 additional soft tissue sarcomas with complex rearrangements between YAP1 and KMT2A, two soft tissue sarcomas with VIM–KMT2A (patients #S1–S2), and 16 soft tissue sarcomas with KMT2A fusions to unique non-YAP1 non-VIM partners (patients #S3–S18)." (PMID 32461620, 2020).